MGMT (O-6-methylguanine-DNA methyltransferase)
Diseases named in the same sentence as MGMT in open-access papers (continued):
Sharing a sentence is not in itself a finding about the gene and the disease.
primitive neuroectodermal tumor (3 papers, 2006 to 2025). A malignant neoplasm that originates in the neuroectoderm. "A gross total resection was performed and the pathology showed GBM with primitive neuroectodermal tumor (PNET) component (MGMT promoter unmethylated, EGFR not amplified, 1p/19q co-deletion negative)." (PMID 24884522, 2014).
rectal tumors (3 papers, 2017 to 2019). "CYT-high rectal tumors on the other hand, had recurrent deletions at loci 3p21.31 (RHOA), 5q22.2 (APC), 10q26.2 (MGMT), 14q32.2 (AKT1, EIF5, YY1), 18q21.2 (SMAD4, MAPK4), and a single amplification in 7p15.3 (STK31)." (PMID 31429779, 2019). "Although these authors proposed MGMT methylation as a new biomarker to differentiate benign and malignant rectal tumors, no relation between MGMT methylation and clinicopathological features was detected." (PMID 31199091, 2019).
renal cell carcinoma (3 papers, 2003 to 2017). "The resistance to TMZ in renal cell cancer may also be due to high MGMT activity since high MGMT activity was observed in pretreatment biopsies from renal cell cancer from four patients who showed no response to TMZ." (PMID 14562026, 2003).
retinoblastoma (3 papers, 2017 to 2023). A malignant tumor that originates in the nuclear layer of the retina. "Aberrant methylation of MGMT has been suggested as an additional epigenetic dysregulation mechanism underlying retinoblastoma." (PMID 28575107, 2017). "For instance, RASSF1A was hypermethylated in 59% of RBs tumors, APC in 6%, while MGMT in 15% of the retinoblastomas analyzed." (PMID 37658463, 2023). "The methyltransferase MGMT (p < 0.05, FC = −4.8) and RB1 (p < 0.05, FC = −4.36) were significantly downregulated in Rb tumors." (PMID 35626705, 2022).
serous carcinoma (3 papers, 2018 to 2021). "MGMT hypermethylation was described as common in most histological subtypes, with the exception of serous carcinoma." (PMID 35008168, 2021). "Our results are in concordance with the reported findings that MGMT methylation is detected at a low occurrence in serous carcinoma." (PMID 35008168, 2021). "MGMT promoter methylation was significantly correlated with pathological types, and it was significantly lower in serous carcinomas than in non-serous carcinomas." (PMID 29882921, 2018). "On the other hand, in serous carcinomas, only 51% and 31% of the tumors were found hypermethylated for ADAMTS12 and MGMT, respectively." (PMID 29882921, 2018). "We observed that complete methylation of MGMT was present in endometrioid (60%, 18/30), mucinous (33%, 10/30), and germ cell (86%, 6/7) subtypes, but almost absent in serous carcinoma (3%, 1/35)." (PMID 29882921, 2018).
serous ovarian cancer (3 papers, 2018 to 2021). "In the present study, we examined the methylation status of six gene promoters (BRCA1, CST6, MGMT, RASSF10, SLFN11 and USP44) in high-grade serous ovarian cancer (HGSOC)." (PMID 35008168, 2021). "For example, tumor suppressor Ras association domain family member 1 (RASSF1A) and O6-methylguanine DNA methyltransferase (MGMT) are lost in invasive ovarian cancer, while Multiple Sclerosis (MS1) and Wilm’s tumor (WT1) are largely lost in endometroid ovarian cancer but not in serous ovarian cancer." (PMID 31426393, 2019).
squamous cell carcinoma (3 papers, 2007 to 2010). A carcinoma arising from squamous epithelial cells. "Squamous cell carcinomas revealed frequent promoter methylation, that is in >40% of cases, of CDH13 (nine out of 16: 56.3%), DAPK1 (nine out of 16: 56.3%), MGMT (15 out of 16: 93.8%) and CADM1 (nine out of 16: 56.3%)." (PMID 17971771, 2007).
testicular germ cell tumor (3 papers, 2017 to 2024). A germ cell tumor arising from the testis. "ADAMTS12 and MGMT were hypermethylated in almost all of the endometrioid, mucinous, and germ cell tumors." (PMID 29882921, 2018).
viral infection (3 papers, 2003 to 2010). "We used lentiviral vectors that inhibited both HIV-1 and simian immunodeficiency virus (SIV)/HIV-1 (SHIV) chimera virus infection, and also expressed a P140K mutant methylguanine methyltransferase (MGMT) transgene to select gene-modified cells by adding chemotherapy drugs." (PMID 19888329, 2009). "A correlation between the promoter methylation status and viral infection, although it was weak, intimated that hepatitis viral infections could play a role in the CpG methylation of the MGMT promoter." (PMID 12592365, 2003). "DNMT1 (MIM 126375) and MGMT (MIM 156569) are involved in DNA methylation and repair, respectively, two processes that are often dysregulated during viral infection." (PMID 20174570, 2010). "In contrast to the MGMT, there was no methylation in hMLH1-positive HCCs, noncancerous, and normal liver tissues with or without hepatitis viral infection (data not shown), suggesting no relation between hMLH1 promoter methylation and viral infections." (PMID 12592365, 2003).
anaplastic oligoastrocytoma (2 papers, 2019 to 2020). An oligoastrocytoma characterized by the presence of increased cellularity, nuclear atypia, pleomorphism, and high mitotic activity. "The pathological diagnosis was anaplastic oligoastrocytoma (grade 3, MGMT unmethylated, IDH mutant and no 1p19q codeletion)." (PMID 30791546, 2019).
anaplastic thyroid cancer (2 papers, 2019 to 2022). "CpG island methylation of tumor-related promoters including RASSF1, MGMT, and SLC5A8 occurs preferentially in undifferentiated thyroid carcinoma." (PMID 31754358, 2019).
bladder (2 papers, 2014 to 2018). "Here, we show that 2%, i.e., 6 out of 368 bladder patients, showed O6-methylguanine-DNA methylftransferase (MGMT) promoter hypermethylation which is in line with previous reports." (PMID 29445424, 2018).
brainstem glioma (2 papers, 2016 to 2017). "For example, we cannot confirm the effect of MGMT promoter methylation on chemotherapy outcome of brainstem glioma, because only seven cases with MGMT promoter methylation were in this study." (PMID 29137285, 2017). "A previous study found positive MGMT staining (correlates with an unmethylated MGMT promoter) by the IHC method in 64.7% of adult brainstem gliomas." (PMID 29137285, 2017). "Importantly, MGMT promoter methylation was unevenly distributed between the different groups of brainstem gliomas." (PMID 29137285, 2017). "There was no report regarding to the prevalence of MGMT promoter methylation in brainstem gliomas, except one study reporting that positive MGMT staining by immunohistochemistry (correlate with unmethylated MGMT promoter) was found in 64.7% of adult brainstem gliomas." (PMID 29137285, 2017). "The frequency of MGMT promoter methylation in adult brainstem glioma has not been adequately evaluated, although positive MGMT expression (correlating with an unmethylated MGMT promoter) was found in 64.7% of cases in one series." (PMID 27556016, 2016).
carcinoid (2 papers, 2022 to 2024). "MGMT promoter methylation was present in 33% (3/9) patients with typical carcinoid, in 22% (2/9) patients with atypical carcinoid, in 22% (8/37) patients with SCLC and in 8% (1/12) patient with LCNEC." (PMID 35677534, 2022). "The lack of benefit from this treatment in some NETs, and in carcinoids specifically, may be explained by the dependency of TMZ response on poor MGMT expression." (PMID 38817857, 2024).
carcinoid tumours (2 papers, 2020 to 2023). "Alu methylation was significantly inversely correlated with MGMT promoter methylation, with low levels of Alu methylation found in patients with well-differentiated PNETs and carcinoid tumours, who had MGMT methylation." (PMID 37434653, 2023). "In this study, we examined the MGMT and GLUT2 status in gastrointestinal neuroendocrine neoplasm (NEN)." (PMID 33287738, 2020).
cholangiocarcinoma (2 papers, 2020 to 2024). A carcinoma that arises from the intrahepatic biliary tree (intrahepatic cholangiocarcinoma) or from the junction, or adjacent to the junction, of the right and left hepatic ducts (hilar cholangiocarcinoma). "We showed that methylation of the MGMT promoter region resulted in a higher proliferation rate among the three cell lines tested, which has also been described in cholangiocarcinoma." (PMID 38357209, 2024).
colon adenocarcinoma (2 papers, 2022 to 2025). "Two of the 4 PDX models with MGMT promoter methylation (625472-104-R and 997537-175-T, both colon adenocarcinomas) that did not respond to either single agent temozolomide or the combination with veliparib had very low MLH1 mRNA levels (log2[normalizedCount+1] < 4)." (PMID 40458731, 2025).
diabetes (2 papers, 2024). "Altogether, it seems that there is a need for more rigorous trials to evaluate these effects, considering pivotal factors such as MGMT promoter status and excluding patients with diabetes." (PMID 39267853, 2024). "Our findings encourage scientists to conduct more well-designed studies that take into account crucial factors concerning metformin and GBM research, including MGMT promoter status and GBM patients without diabetes." (PMID 39267853, 2024).
fibrosarcoma (2 papers, 2014 to 2023). A malignant mesenchymal fibroblastic neoplasm affecting the soft tissue and bone. "The fibrosarcoma had negative expression of MGMT, ERCC1, hMSH2, and hMLH1, while pancreas of group C had positive expression of MGMT, ERCC1, hMSH2, and hMLH1." (PMID 24502441, 2014). "However, many GBM cells with high MGMT expression are not sensitive to TMZ treatment; MGMT expression can be increased through the rat sarcoma virus (RAS)/rapidly accelerated fibrosarcoma (RAF)/extracellular signal‐regulated kinase (ERK) signaling pathway, leading to TMZ resistance." (PMID 36176197, 2023). "All pancreas of group C had positive expression of MGMT, ERCC1, hMSH2, and hMLH1 and two cases of fibrosarcoma showed a negative expression." (PMID 24502441, 2014).
gastric adenocarcinoma (2 papers, 2016 to 2017). "In conclusion, the results of this study indicated that MGMT gene-promoter hypermethylation was significantly associated with the risk of GC, especially in Asians and gastric adenocarcinoma." (PMID 28445279, 2017). "According to the subgroup of gastric adenocarcinoma, a significant result was also detected, and the carriers of MGMT promoter hypermethylation have 3.47 times higher risk of GC than those of hypomethylation." (PMID 28445279, 2017). "In the subgroup analysis based on GC subtype, the MGMT promoter hypermethylation significantly increased the risk of gastric adenocarcinoma (OR = 3.47, CI = 1.06–11.35, P < .05)." (PMID 28445279, 2017). "When stratified by cancer subtype, the results indicated that the frequency of MGMT promoter hypermethylation was significantly higher in gastric adenocarcinoma than in control group (OR = 3.47, CI = 1.06–11.35, P < .05)." (PMID 28445279, 2017). "We have found no information in the scientific literature regarding the correlation of MGMT and MLH1 promoter methylation in stomach adenocarcinoma tissues." (PMID 26810771, 2016).
gynecological cancer (2 papers, 2017 to 2020). "The initial search identified 429 studies on breast and gynecological cancers risk and/or clinical outcome assessment for MGMT hypermethylation." (PMID 28986566, 2017). "We conducted a meta-analysis to assess the association between hypermethylation of MGMT promoter and the risk of breast and gynecologic cancers." (PMID 28986566, 2017). "Nevertheless, for breast and gynecologic cancers, although many studies have explored the association between their risks and MGMT promoter hypermethylation, the results remain inconsistent." (PMID 28986566, 2017). "The pooled results showed that MGMT promoter methylation status was significantly associated with an increased risk of breast and gynecological cancers in women (OR = 4.37, 95% CI: 2.68–7.13, P < 0.05)." (PMID 28986566, 2017). "The pooled results showed that MGMT promoter methylation status was significantly associated with an increased risk of breast and gynecologic cancers (OR = 4.37, 95% CI: 2.68–7.13, P < 0.05)." (PMID 28986566, 2017). "A comprehensive search was conducted in PubMed and Embase electronic databases up to 19th August 2017 for studies about the association between MGMT promoter hypermethylation and breast and gynecologic cancers." (PMID 28986566, 2017). "We believe that this is the first quantitative study to assess the association between hypermethylation of MGMT promoter and the risk of breast and gynecologic cancers." (PMID 28986566, 2017). "When all studies were pooled into the meta-analysis, cancer risk associated with MGMT promoter hypermethylation was significant in breast and gynecological cancers." (PMID 28986566, 2017). "This meta-analysis indicated that MGMT hypermethylation was significantly associated with the risk of breast and gynecological cancers, and it may be utilized as a valuable biomarker in early diagnostics and prognostication of these cancers." (PMID 28986566, 2017). "Therefore, we conducted this systematic review and meta-analysis to assess the association between hypermethylation of MGMT promoter and the risk of breast and gynecologic cancers." (PMID 28986566, 2017). "The pooled results were not significant changed for random effects model (OR = 3.76, 95% CI: 2.30–6.15, P < 0.05), indicating that patients with hypermethylated MGMT may have an increased risk in breast and gynecological cancers." (PMID 28986566, 2017). "The role of the promoter methylation of O6-methylguanine-DNA methyltransferase (MGMT) remains controversial for breast and gynecologic cancers." (PMID 28986566, 2017).
hyperplastic polyp (2 papers, 2011 to 2013). A polyp found mainly in the stomach and colon. "The overall incidence of methylation in all hyperplastic polyps tested were MLH-1 10%, p16INK4a 26%, MGMT 19%, MINT 1 28%, and MINT 31 26%." (PMID 22312515, 2011).
intrahepatic cholangiocarcinoma (2 papers, 2022). A carcinoma that arises from the intrahepatic bile duct epithelium in any site of the intrahepatic biliary tree. "In intrahepatic cholangiocarcinoma, MGMT knockdown promotes cancer cell proliferation." (PMID 35723009, 2022). "MASTER: Molecularly Aided Stratification for Tumor Eradication Research; eCCA: extrahepatic cholangiocarcinoma; iCCA: intrahepatic cholangiocarcinoma; IQR: interquartile range; MGMT: O6‐methylguanine DNA methyltransferase; NA: not available; NOS: not otherwise specified." (PMID 35621918, 2022).
invasive carcinoma (2 papers, 2013 to 2025). A carcinoma that is not confined to the epithelium, and has spread to the surrounding stroma. "DNA methylation patterns involving genes like CCNA1, C13ORF18, DAPK, HIC-1, HIN-1, MGMT, RAR-beta, and RASSF1A were also modeled as influential epigenetic factors affecting different transition states from normal tissue to invasive carcinoma." (PMID 40649795, 2025).
large cell neuroendocrine carcinoma (2 papers, 2018 to 2022). A usually aggressive carcinoma composed of large malignant cells which display neuroendocrine characteristics. "Currently, the status of MGMT promoter methylation and 1p/19q co-deletion in pulmonary carcinoid (PC) and large-cell neuroendocrine carcinoma (LCNEC) is not reported." (PMID 29914531, 2018).
laryngeal squamous cell carcinoma (2 papers, 2015 to 2021). A squamous cell carcinoma that arises from the larynx. "The aim of the present study was to investigate the association between O6-methylguanine-DNA methyltransferase (MGMT) gene expression levels, and DNA methylation status and histone modifications in laryngeal squamous cell carcinoma (LSCC)." (PMID 25452816, 2015). "Furthermore, methylation-specific polymerase chain reaction (MSP) and reverse transcription (RT)-quantitative polymerase chain reaction (qPCR) were used to detect the association between MGMT gene expression levels and DNA methylation status in laryngeal squamous cell carcinoma (LSCC) tissues." (PMID 25452816, 2015).
low grade glioma (2 papers, 2021). A grade I or grade II glioma arising from the central nervous system. "Patients with low-grade gliomas (LGGs) harboring O6-methylguanine-DNA methyltransferase promoter nonmethylation (MGMT-non-pM) have a particularly short survival and are great resistance to chemotherapy." (PMID 34412650, 2021).
lung NETs (2 papers, 2022 to 2024). "In other retrospective series, MGMT is methylated in 0–27% of lung NETs." (PMID 35677534, 2022). "SSTR2 and MGMT are well-recognized predictive markers for SSA and temozolomide efficacy, respectively, and are commonly discussed in gastroenteropancreatic and pulmonary neuroendocrine tumors." (PMID 39061142, 2024). "No prospective data about the incidence of MGMT promoter methylation is available in lung NETs." (PMID 35677534, 2022).
mesenchymal tumors (2 papers, 2020 to 2025). "Mean MGMT methylation was lowest in mesenchymal tumors; however, highest percentage of MGMT unmethylated tumors was found in the RTK I subgroup." (PMID 32991787, 2020).
metastatic colorectal cancer (2 papers, 2023 to 2024). "In patients with microsatellite-stable (MSS) and O6-methylguanine-DNA methyltransferase (MGMT)-silenced metastatic colorectal cancer (mCRC), the researchers administered two cycles of temozolomide first as an immunosensitizer, and then a combination of low-dose ipilimumab and nivolumab." (PMID 38817857, 2024). "For metastatic colorectal cancer, the successful use of alkylator combinations in the future will require a careful selection of biomarkers, which should include a quantitative measure of MGMT protein expression, as supported by our findings." (PMID 37387791, 2023). "However, promoter hypermethylation of O6-methylguanine DNA methyltransferase (MGMT) is identified in approximately 40% of metastatic colorectal cancer." (PMID 37387791, 2023).
neutropenia (2 papers, 2005 to 2022). A decrease in the number of neutrophils found in the blood. "However, regarding toxicity, we found that the grade of thrombocytopenia during cycle 1 was correlated with low baseline levels of MGMT though this was not evident for neutropenia." (PMID 16136028, 2005).
pancreatic neuroendocrine neoplasm (2 papers, 2023 to 2025). A neoplasm with neuroendocrine differentiation that arises from the pancreas. "A recent prospective phase II study (ECOG‐ACRIN E2211) demonstrated that MGMT deficiency was associated with a significant response to capecitabine and temozolomide (CAPTEM) in pancreatic neuroendocrine neoplasms (NENs); however, routine MGMT analysis in NENs was not recommended." (PMID 39825572, 2025).
papillary thyroid carcinoma (2 papers, 2017 to 2021). "Papillary carcinoma cases also show an increased incidence of low MGMT compared to hyperplastic nodules." (PMID 33976347, 2021).
paraganglioma (2 papers, 2020 to 2023). A benign or malignant neoplasm arising from paraganglia located along the sympathetic or parasympathetic nerves. "This was attributed to the decreased expression of the DNA repair enzyme O6-methylguanine-DNA methyltransferase (MGMT) consequent to its promoter hypermethylation, as detected in patient SDHB-mutated paraganglioma and pheochromocytoma metastasis." (PMID 32575796, 2020).
parathyroid tumor (2 papers, 2019 to 2024). "The parathyroid tumor had high methylguanine-DNA methyltransferase (MGMT) promoter methylation status, which is a known predictor of response to temozolamide." (PMID 39011405, 2024). "The parathyroid tumor tissue demonstrated high O6‐methylguanine DNA methyltransferase (MGMT) promoter methylation status, a known predictor of positive temozolomide treatment response in other tumors." (PMID 31044184, 2019).